PGR (progesterone receptor)
Diseases named in the same sentence as PGR in open-access papers (continued):
Sharing a sentence is not in itself a finding about the gene and the disease.
breast cancer (continued). "Luminal B1 breast cancer is a subtype within the broader Luminal B category, characterized by estrogen receptor (ER) positivity, variable progesterone receptor (PR) expression, HER2 negativity, and a high Ki-67 proliferation index." (PMID 40149262, 2025). "This study sought to address the gaps in knowledge by investigating the effects of exposing progesterone receptor (PR)-positive human breast cancer cells to different progestins on the transcriptional expression of primiR-190 and primiR-199a1." (PMID 40026926, 2025). "Accordingly, loss of GATA3 expression has been reported to be associated with basal-like breast cancer aggressiveness, HER2 overexpression, oestrogen and progesterone receptor negativity, and reduced survival." (PMID 40585280, 2025). "Luminal A breast cancer, characterised by estrogen receptor positivity, progesterone receptor positivity and human epidermal growth factor receptor 2 negativity, typically has a favourable prognosis." (PMID 41778178, 2025). "Except that, B7H3 expression was high in patients with common immunohistochemical indicators of breast cancer such as progesterone receptor (p = 0.006), estrogen receptor (p < 0.001), HER2 (p < 0.001), and PAM50 (p < 0.001)." (PMID 39735676, 2025). "Triple negative breast cancer (TNBC) accounts for approximately 10–20% of breast cancer cases and lacks expression of the estrogen receptor, progesterone receptor, and human epidermal growth factor receptor-2." (PMID 40313394, 2025). "Materials and methods: A cross-sectional study of 50 consecutive cases of primary breast cancer, which are ER/progesterone receptor (PR) positive, has been included in the study." (PMID 41439079, 2025). "Like BIG 1-98, the target trial would recruit postmenopausal women with estrogen or progesterone receptor–positive breast cancer." (PMID 40838592, 2025). "Estrogen receptor (ER), progesterone receptor (PR), and Ki67 concordance between primary breast carcinoma and corresponding local recurrent cases was analyzed case by case." (PMID 39929942, 2025). "Evaluating progesterone receptor status is crucial for determining breast carcinoma prognosis and helps to categorize these tumors into luminal A or luminal B subtypes, highlighting its relevant role in developing effective prediction models." (PMID 39858055, 2025). "Triple negative breast cancer (TNBC) is a subtype of breast cancer that lacks estrogen receptor (ER), progesterone receptor (PR), and HER2 expression." (PMID 39469630, 2024). "It has been reported that estrogen receptor or progesterone receptor positive luminal subtype breast cancer has a lower pCR rate in NAT, which is also reflected in the results of this study." (PMID 39403373, 2024). "Ashwagandha has been found to possess a potential for treating breast cancer, especially estrogen receptor/progesterone receptor (ER/PR)-positive and triple-negative breast cancer." (PMID 39057095, 2024). "For decades, the treatment of breast cancer has been based on classification according to estrogen receptor (ER), progesterone receptor (PR), and human epidermal growth factor receptor 2 (HER2) status." (PMID 39484719, 2024). "One of the features of breast cancer tumour cells is the presence of three important receptors: oestrogen receptor (ER), progesterone receptor (PR) and human epidermal growth factor receptor 2 (HER2)." (PMID 38540131, 2024). "Hormone receptor (HR)-positive breast cancer constitutes a prevalent subtype characterized by the presence of estrogen receptor (ER) and/or progesterone receptor (PR) positive cells, enabling hormonal stimulation of cancer growth." (PMID 38649821, 2024). "If there are more estrogen and/or progesterone receptors than those of normal ones in breast cancer cells, it is expressed as estrogen and/or progesterone receptor positive and constitutes the majority (70%) of patients diagnosed with breast cancer." (PMID 38544901, 2024).
breast cancer (continued). "Estrogen receptor (ER) and progesterone receptor (PR) positive tumors, termed hormonal receptor-positive tumors, account for most breast cancer presentations." (PMID 39469406, 2024). "Copper depletion strategies are being explored with ATN-224, in a phase II trial for recurrent or advanced estrogen and progesterone receptor-positive breast cancer (NCT00674557)." (PMID 39867656, 2024). "In breast cancer cells and uterine leiomyoma tissues, P4 acts on the progesterone receptor (PGR) to increase mitochondrial membrane potential and ATP production, contributing to the restoration of mitochondrial functions." (PMID 39138434, 2024). "TNBC is given the name due to its three-fold deficiency in the estrogen receptor (ER), progesterone receptor (PR), and human epidermal growth factor receptor 2 (HER2), which are considered the main treatment targets in breast cancer patients." (PMID 38538285, 2024). "Triple-negative breast cancer (TNBC) is a type of breast cancer that lacks expression of estrogen receptor (ER), progesterone receptor (PR), and unamplified human epidermal growth factor receptor 2 (HER2) on the cell surface." (PMID 39339179, 2024). "Breast cancer is classified into three major clinical subtypes depending on the expression of the hormone receptors (HR) – estrogen receptor (ER) and progesterone receptor (PR) – and the human epidermal growth factor receptor 2 (HER2)." (PMID 38831405, 2024). "This lethal breast cancer subtype is histologically classified as estrogen receptor (ER), progesterone receptor (PR), and human epidermal growth factor receptor 2 [HER2]-negative and accounts for approximately 20% of all diagnosed breast cancer cases." (PMID 39328201, 2024). "For example, prolactin stimulates ER expression and works in concert with progesterone receptor to promote autocrine secretion-mediated mammary epithelial cell and breast cancer proliferation." (PMID 38553763, 2024). "MCF-7 is a commonly used breast cancer cell line, it is ER-positive and progesterone receptor (PR)-positive and belongs to the luminal A molecular subtype." (PMID 38711049, 2024). "Progesterone receptor (r = 0.439) is induced by ER-α and plays an important role in regulating ER-α protein, thereby it functions as an important biomarker for breast cancer treatment and prognosis." (PMID 38413598, 2024). "Gallen Breast Cancer Consensus proposed a classification of breast cancer into four molecular subtypes based on estrogen receptor (ER), progesterone receptor (PR), human epidermal growth factor receptor 2 (HER2), and Ki-67 proliferation index." (PMID 39845328, 2024). "Breast cancer is classified into different subtypes depending on the expression of the estrogen receptor alpha (ERα), progesterone receptor (PR) and overexpression of the human epidermal growth factor receptor 2 (HER-2)." (PMID 38338747, 2024). "Breast cancer can be classified into subtypes based on the expression of estrogen receptor (ER), progesterone receptor (PR), and human epidermal growth factor receptor 2 (HER2)." (PMID 38565949, 2024). "Loss of GATA3 expression in breast cancer has been linked to poor prognosis with a higher tumor T stage, HER2 overexpression, estrogen and progesterone receptor negativity, and reduced survival." (PMID 38668712, 2024). "AURKA promotes distant metastases in ERα-positive breast cancer cells and its overexpression is strongly linked to decreased survival, high nuclear grade, and elevated HER-2/neu and progesterone receptor levels in breast cancer." (PMID 39334449, 2024). "In routine clinical practice regarding breast cancer, the subtypes are commonly discerned through immunohistochemical markers, such as the estrogen receptor (ER), progesterone receptor (PR), and human epidermal growth factor receptor 2 (HER2)." (PMID 38581481, 2024).
breast cancer (continued). "Estrogen receptor (ER), human epidermal growth factor receptor 2 (HER2), and progesterone receptor expression status show significant heterogenicity in breast cancer and can be used to categorize the disease into distinct classes." (PMID 39323672, 2024). "We compared the number of clusters detected with several variables related to breast cancer, including estrogen receptor (ER) status, progesterone receptor (PgR) status, survival time, and survival status for ten years." (PMID 38350879, 2024). "Different subtypes of breast cancer are classified based on the expression of three common biomarkers: progesterone receptor (PR), estrogen receptor (ER), and human epidermal growth factor receptor 2 (HER2)." (PMID 39275659, 2024). "Of these breast cancers, approximately 70% are diagnosed as hormone receptor positive (HR+) based on detectable expression levels of the estrogen receptor α (ERα) and/or progesterone receptor (PR)." (PMID 38567308, 2024). "Keeping in view the pharmacological potential of natural products and the speed and accuracy, this study utilizes Pharmacophore-based virtual screening and molecular simulation to target the human progesterone receptor (HPR) in breast cancer treatment." (PMID 38514638, 2024). "Molecular subtypes for breast cancer consider the expression of Ki-67, estrogen receptor (ER), progesterone receptor (PR) and the human epidermal growth factor receptor 2 (HER2)." (PMID 38896333, 2024). "Survival analysis using available databases indicated that high IGFBP-6 levels improve overall survival in progesterone receptor positive breast cancers." (PMID 39698031, 2024). "Luminal B tumors that show high levels of the protein Ki-67 and are positive for HRs (estrogen receptor [ER] and/or progesterone receptor) are typified by luminal B breast cancer." (PMID 39449897, 2024). "The finding that GEX of ESR1 and PGR can be used to predict tamoxifen benefit is clinically useful since GEX analysis is already routinely performed in patient subgroups with early breast cancer." (PMID 38587062, 2024). "Given the vital role of the Human progesterone receptor (HPR) in breast cancer, it represents a critical therapeutic target for the treatment of breast cancer." (PMID 38514638, 2024). "The immunohistochemical detection of cancer biomarkers that guide treatment has been well validated, and some of them, such as ER and progesterone receptor (PgR) in breast cancer, have been approved by the Food and Drug Administration (FDA)." (PMID 39246627, 2024). "Molecular subtyping of breast cancer patients based on ER, PgR, HER2 and Ki67 status is of great importance and is routinely used for the stratification of treatment personalization and prognostication." (PMID 39183273, 2024). "We noted that higher levels of macrophage infiltration corresponded to reduced ESR1 or PGR expression in breast cancer and luminal breast cancer." (PMID 38339428, 2024). "Breast cancer (BC) is a heterogenous disease, with prognosis and treatment options depending on Estrogen, Progesterone receptor, and Human Epidermal Growth Factor Receptor-2 (HER-2) status." (PMID 38500769, 2024). "A biopsy confirmed recurrent ER+/PR+/HER2- (estrogen receptor-positive/progesterone receptor-positive/human epidermal growth factor receptor 2-negative) breast cancer." (PMID 39553033, 2024). "Luminal A subtype of breast cancers are highly differentiated tumors exhibiting increased expression of hormone receptors, ER alpha, and progesterone receptor (PR), and they show good prognosis." (PMID 39329990, 2024). "To determine the effect of NHRs on PCDH19 expression we screened a set of breast cancer cell lines to identify one that expresses ERα, PGR and AR." (PMID 38280856, 2024). "Breast cancer is classified into different subtypes based on the presence or absence of specific protein markers, namely estrogen receptor α (ERα), progesterone receptor (PR), and ERBB2 (also known as Human Epidermal Growth Factor Receptor 2, HER2)." (PMID 39519045, 2024).
breast cancer (continued). "Breast cancer was divided into four distinct molecular subtypes, dependent on the expression profiles of estrogen receptor (ER), progesterone receptor (PR), human epidermal growth factor receptor 2 (HER2), and Ki67." (PMID 39512692, 2024). "Breast cancer can be classified upon the over-expression of three receptors: the estrogen receptor alpha (ER-α), the progesterone receptor (PR), and the human epidermal growth factor receptor 2 (HER2)." (PMID 39201674, 2024). "Breast cancer subtyping, determined by hormone receptor levels such as estrogen receptor (ER), progesterone receptor (PR), and human epidermal growth factor receptor 2 (HER2), is crucial for predicting patient survival rates." (PMID 39684741, 2024). "Breast cancer can be divided into different subtypes based on the presence of its molecular markers: estrogen receptor (ER), progesterone receptor (PR), and human epidermal growth factor receptor 2 (HER2)." (PMID 38254674, 2024). "The most frequent breast cancer type is the hormone receptor-positive (HR+), which expresses the estrogen receptor (ER) and/or progesterone receptor (PR) and accounts for approximately 75% of BC cases." (PMID 40027941, 2024). "In this study, we employed pharmacophore-based virtual screening and molecular simulations to identify natural product-based inhibitors of human progesterone receptor (PR) in breast cancer treatment." (PMID 38514638, 2024). "Currently, clinically, breast cancer is classified and treated differently based on the expression differences in the estrogen receptor, progesterone receptor, and human epidermal growth factor receptor in patients." (PMID 39253075, 2024). "Our results indicate that IGFBP-6 is induced by progesterone in T47D breast cancer cells and stabilizes progesterone receptor levels." (PMID 39698031, 2024). "Breast cancer is subtyped based on molecular profiling for the expression of hormone receptors [progesterone receptor (PR), estrogen receptor alpha (ER)] and human epidermal growth factor receptor 2 (HER2)." (PMID 38473207, 2024). "In breast cancer, the estrogen receptor (ER) and the progesterone receptor (PgR) play a vital role in determining the responsiveness to endocrine therapies." (PMID 38514638, 2024). "Immunohistochemical examination of ER and PgR is strongly recommended for all primary breast cancers." (PMID 37934318, 2024). "Breast cancer is classified into four molecular subtypes based on positivity for estrogen receptor (ER), progesterone receptor (PR), Her2 neu, and Ki67 index: luminal A, luminal B, Her 2-enriched, and triple-negative." (PMID 39469406, 2024). "The treatment of breast cancer is largely determined by protein expression assays of estrogen receptor, progesterone receptor, and Her2/neu (HER2) status." (PMID 38571852, 2024). "MCF-7 cells belong to the Luminal A subtype of breast cancer cells, characterized by the presence of estrogen receptor (ER) and progesterone receptor (PR)." (PMID 39629082, 2024). "One of the lncRNA, SOX2 has been identified in 43% of basal cell-like breast cancers, and it is significantly associated with CK5/6, EGFR, and vimentin immunoreactivity, while showing an inverse association with estrogen and progesterone receptor status." (PMID 38649821, 2024). "The majority of breast cancer patients bear tumors that express druggable targets: estrogen receptor (ER), progesterone receptor (PR), and human epidermal growth factor receptor 2 (HER2)." (PMID 38317231, 2024). "Triple-negative breast cancer (TNBC) is referred to as a subtype of breast cancer that lacks estrogen receptor (ER), progesterone receptor (PR) expression, and human epidermal growth factor receptor 2 (HER-2) expression/amplification." (PMID 38902343, 2024).
breast cancer (continued). "The present study is the first to explore the breast transcriptome following mifepristone treatment in normal breast tissue in vivo, enhancing the understanding of progesterone receptor antagonism and its potential protective effect against breast cancer." (PMID 39062832, 2024). "Breast cancer, characterized by its heterogeneity, is typically categorized by the status of estrogen receptor, progesterone receptor, and HER2 expression." (PMID 38335435, 2024). "Only women with clinical Stage I–III estrogen or progesterone receptor (hormone receptor/HR)-positive breast cancer who received neoadjuvant endocrine therapy followed by surgery were included." (PMID 37740855, 2024). "In the clinic, breast cancer is screened for the presence of estrogen receptor (ER), progesterone receptor (PR) and amplification of ERBB2/HER2 (HER2)." (PMID 37776423, 2024). "In postmenopausal women, a strong correlation has been observed between the increase in BMI and the incidence of developing breast cancer with positive expression of estrogen receptor alpha (ERα) and progesterone receptor (PR)." (PMID 38768058, 2024). "Triple-negative breast cancer (TNBC) is a malignant and highly metastatic subtype of breast cancer that lacks expression of estrogen receptor (ER), progesterone receptor (PR), and human epidermal growth factor receptor 2 (HER2)." (PMID 38649679, 2024). "There are four molecular subtypes (Luminal A, Luminal B, Her2 and triple negative) of breast cancer (BC), determined by the expression of estrogen receptor (ER), progesterone receptor (PR), human epidermal growth factor receptor 2 (Her2) and Ki-67." (PMID 38713229, 2024). "To study the role of hsa-miR-146a-5p in vitro, we utilized human MCF-7 cells, an estrogen and progesterone receptor positive invasive ductal/breast carcinoma." (PMID 39742358, 2024). "Breast cancer (BC) is classified into four categories based on the expression of hormone receptors (HRs): estrogen receptor positive (ER+), progesterone receptor positive (PR+), and human epidermal growth factor receptor positive (HER2+)." (PMID 39598723, 2024). "Triple-negative breast cancer is a highly aggressive and heterogeneous type of breast cancer (BC) that lacks the expression of estrogen receptor (ER), progesterone receptor (PR), and human epidermal growth factor receptor 2 (HER2)." (PMID 39430759, 2024). "(2020), the immunohistochemical panel for canine and feline mammary carcinomas should be composed of the expressions of the oestrogen receptor (ER), progesterone receptor (PR), Ki-67 and COX-2." (PMID 38751991, 2024). "Estrogen receptor (ER), progesterone receptor (PR), and human epidermal growth factor receptor 2 (Her2Neu) are the three widely used biomarkers for analysing the prognosis of breast carcinoma." (PMID 39435217, 2024). "At diagnosis, breast cancer patients are categorized into different subtypes based on expression of three receptors: estrogen receptor-alpha (ERα), progesterone receptor (PR), and human epidermal growth factor receptor 2 (HER2)." (PMID 37841259, 2023). "Historically, breast cancer was classified according to the expression of the estrogen receptor (ER), progesterone receptor (PR), and human epidermal growth factor receptor 2 (HER2)." (PMID 37575061, 2023). "Breast cancer can be classified into molecular subtypes based on the presence of three receptors: estrogen receptor (ER), progesterone receptor (PR), and human epidermal growth factor receptor 2 (HER2)." (PMID 36737605, 2023). "Studies have shown a controversial association between PgR levels and benefit from CDK4/6i in breast cancer." (PMID 36717797, 2023). "Meanwhile, a relatively higher level of mean INO80 expression was found in patients with luminal breast cancer classified as ER and/or progesterone receptor (PR) IHC-positive." (PMID 38020889, 2023). "Interleukin which shows an increase in breast cancer is inversely correlated with estrogen receptor (ER) and progesterone receptor status." (PMID 37520880, 2023).